REN (renin)
Diseases named in the same sentence as REN in open-access papers (continued):
Sharing a sentence is not in itself a finding about the gene and the disease.
portal hypertension (51 papers, 2010 to 2025). Increased blood pressure in the portal venous system. "Portal hypertension leads to vasodilatation of splanchnic vessels, decrease in systemic vascular resistance, and activation of the renin-angiotensin-aldosterone causing vasoconstriction of renal arteries." (PMID 33381474, 2020). "In patients with portal hypertension, hormones like aldosterone and renin have been suggested to cause thinning of the arterial wall." (PMID 32983447, 2020). "Low effective intravascular volume, along with systemic vasodilation (due to portal hypertension) and increased intraabdominal pressures (due to ascites), causes renal hypoperfusion and subsequent activation of the renin‐angiotensin‐aldosterone axis, leading to sodium and water retention." (PMID 40458689, 2025). "Indomethacin has been shown to block renin in alcohol-associated liver disease, although its mechanism is unknown." (PMID 38891995, 2024). "Instead, the greatest utility of plasma renin levels may be for prognostic purposes to identify patients at high risk for disease and portal hypertension progression." (PMID 38891995, 2024). "Moreover, in patients with LC, high renin concentration has been reported to be associated with a poor prognosis and renin has been suggested to be an indicator of portal hypertension and increased risk of ascites." (PMID 36143954, 2022). "Ascites formation is primarily driven by portal hypertension and subsequent activation of the renin-angiotensin-aldosterone system (RAAS)." (PMID 40757205, 2025). "Despite the theoretical rationale behind targeting the renin-angiotensin system, these findings underscore the limited efficacy of ARBs in mitigating the hemodynamic alterations characteristic of cirrhotic portal hypertension." (PMID 39997697, 2025). "This variability in effect corresponds with previous studies on the renin-angiotensin system in portal hypertension, linking it to complex pathways, high intrahepatic pressure, and splanchnic vasodilation." (PMID 40452676, 2025). "The compensatory elevation in renin and AngII levels becomes maladaptive, causing further arterial renal vasoconstriction and decreasing GFR, eventually leading to hepatorenal syndrome (HRS) in severe cases." (PMID 38891995, 2024). "The renin–angiotensin system (RAS) in liver disease is complex and its numerous roles are still incompletely understood." (PMID 38891995, 2024). "Impaired liver function activates the renin–angiotensin–aldosterone system, which exacerbates liver fibrosis, liver function and portal hypertension, eventually leading to a vicious cycle." (PMID 36241992, 2022). "Animal models and clinical studies suggest an influence of angiotensin II (AngII) on the pathogenesis of liver diseases via the renin–angiotensin system." (PMID 35229169, 2022). "One possibility is that, in patients with cirrhosis, effective circulatory volume decreases, as portal hypertension progresses, and subsequently renin-angiotensin aldosterone system is stimulated." (PMID 32321533, 2020). "As a consequence, inhibition of renin leads to improved liver fibrosis and reduction in portal hypertension." (PMID 32392802, 2020). "Inhibition of renin, which is upstream of both pathways, leads to improved liver fibrosis and portal hypertension, suggesting a preponderance of the classic AT1R mediated pathway." (PMID 31406138, 2019). "NT-proBNP as a contraregulatory mechanism for decreasing portal hypertension induces natriuresis, vasodilation activation with a concomitant inhibition of the renin-angiotensin-aldosterone system and adrenergic activity." (PMID 22911531, 2012). "Another interesting finding is the reduced awake-asleep variation of BP and HR in patients with more severe portal hypertension, as suggested by higher renin and aldosterone levels." (PMID 21143998, 2010).
portal hypertension (continued). "Increased plasma renin activity in decompensated cirrhosis reflects reduced effective blood or extracellular fluid volume, consequent to portal hypertension and mesenteric vasodilation, with reduction described following albumin infusions for large-volume paracentesis and SBP." (PMID 35333783, 2022). "These authors concluded that direct renin inhibition may serve as a potential and effective therapeutic strategy for the management of portal hypertension." (PMID 36316746, 2022). "Similarly, the consortium investigated the influence of the renin-angiotensin system and its counteracting receptors for hepatic fibrosis and portal hypertension." (PMID 35087852, 2021). "Portal hypertension and peritoneal disease can lead to fluid accumulation in the abdominal cavity through activation of the renin–angiotensin–aldosterone system, sodium and water retention, increased plasma volume, and fluid secretion into the serosa-lined cavity." (PMID 34953487, 2021). "Renin-induced portal hypertension can be ameliorated either by JAK2 inhibitors or Mas agonists." (PMID 31406138, 2019). "However, this concept could not be implemented in the rats in our study, since the mouse renin expression - responsible for the development of liver fibrosis and portal hypertension - was reduced upon cholestatic or toxic liver injury." (PMID 31406138, 2019). "The renin-angiotensin system (RAS) plays a complex and significant role in liver disease pathophysiology, influencing both hepatic fibrosis and portal hypertension." (PMID 41226756, 2025). "Furthermore, the progression of liver disease and portal hypertension leads to progressive vasodilatation, which reduces the effective arterial blood volume and results in the activation of the sympathetic nervous system as well as the renin-angiotensin-aldosterone system (RAAS)." (PMID 35913923, 2022). "In portal hypertension (PHT) there is a functional hemodynamic intrarenal disorder and a strong stimulation of renin–angiotensin–aldosterone system (RAAS) and also a high level of circulating vasopressin." (PMID 20968204, 2010). "Splanchnic vasodilatation, a direct result of portal hypertension, leads to a decrease in effective arterial blood volume (EABV), which then activates homeostatic systems such as the renin-angiotensin system and sympathetic nervous system to promote sodium and water retention and vasoconstriction." (PMID 40144213, 2025). "The SGLT2-I may target neurohumoral pathways and alleviate the renin-angiotensin-aldosterone system (RAAS), an essential system in the pathogenesis of portal hypertension." (PMID 38114915, 2023). "The cardiovascular hormones renin/angiotensin/aldosterone (RAA), brain-type natriuretic peptide (BNP)and arginine-vasopressin (AVP) are key regulators of systemic circulatory homeostasis in portal hypertension (PH)." (PMID 34021479, 2021).
glomerulosclerosis (46 papers, 2011 to 2025). A hardening of the kidney glomerulus caused by scarring of the blood vessels. "Activation of the local and systemic renin-angiotensin system and complement also leads to glomerulosclerosis and tubulointerstitial fibrosis, which leads to loss of renal function." (PMID 37488573, 2023). "In glomerulosclerosis, there is a decrease in downstream peritubular capillary blood flow, which causes glomeruli in these areas to secrete excess renin." (PMID 36835994, 2023). "Multiple mechanisms implicated in the development of proteinuria in glomerulosclerosis, such as oxidative stress and renin–angiotensin–aldosterone system." (PMID 29619864, 2018). "Consistent with marked glomerulosclerosis in UNx-Renin mice, ECM-associated gene expression changes were more pronounced in UNx-Renin mice, in which additional markers of fibrogenesis were significantly upregulated, including Col1a1, Col3a1, Col6a1, Col6a2 and Mmp7." (PMID 34494644, 2021). "Key molecular pathways implicated in FSGS include the activation of the renin-angiotensin-aldosterone system, aberrant TGF-β signaling, and increased oxidative stress, which contributes to podocyte injury and glomerular sclerosis." (PMID 40236664, 2025). "Attenuate the progression of glomerular sclerosis and renal interstitial fibrosis by regulating renin-angiotensin system." (PMID 40182630, 2025). "Conversely, exercise training has been demonstrated to exert a beneficial effect on the progression of glomerulosclerosis and interstitial fibrosis in rats with chronic renal failure by modulating the function of the renal renin-angiotensin system." (PMID 40182630, 2025). "It has been shown that testosterone can increase the oxidative stress of renal cells, can further activate the renin-angiotensin system, and aggravate renal fibrosis and glomerulosclerosis." (PMID 36497080, 2022). "Riociguat improved renal endpoints such as lowering plasma creatinine, reduced glomerulosclerosis, and less renal interstitial fibrosis in low and high renin-models." (PMID 35085251, 2022). "As molecular drivers of glomerulosclerosis in diabetic UNx and UNx-Renin mice, our glomerular gene expression analysis confirmed the upregulation of several fibrogenesis-associated genes (e.g. Col1a1, Col5a1, Col5a3, Fn1 and Mmp14)." (PMID 34494644, 2021). "Quantification of total glomerular periodic acid–Schiff (PAS) mass indicated increased glomerulosclerosis in UNx and UNx-Renin mice compared to db/m controls (both P<0.001), being most advanced in UNx-Renin mice (P<0.001 versus UNx)." (PMID 34494644, 2021). "Col5a3, Fn1 and Mmp14 were upregulated in the kidney cortex and glomeruli of UNx-Renin mice compared to both db/m controls and UNx mice, underscoring the advanced progression of glomerulosclerosis in this model of late-stage DKD." (PMID 34494644, 2021). "Activation of the VDR suppresses renin, has anti‐fibrotic effects, and decreases glomerulosclerosis." (PMID 33026128, 2020). "This is consistent with our findings of a somewhat decreased plasma renin activity in aging rats after uninephrectomy during ongoing nephrogenesis, which develop more prominent glomerulosclerosis than rats uninephrectomized after completion of nephrogenesis." (PMID 29540722, 2018). "Glomerular hyperfiltration activates the renin-angiotensin system, eventually leading to glomerular sclerosis." (PMID 21423692, 2011). "Additionally, vitamin D and its analogs have a positive effect on glomerular sclerosis and interstitial fibrosis by means of immunomodulatory and anti-inflammatory reactions, as well as inhibition of the renin-angiotensin system." (PMID 38996723, 2024). "The extensive glomerulosclerosis in the remnant kidney model may be closely related to immune dysregulation and abnormal activation of the renin-angiotensin system." (PMID 31781634, 2019).
glomerulosclerosis (continued). "Indices of kidney injury, including proteinuria, glomerulosclerosis, and interstitial fibrosis, inflammation, and increased renal medullary and urinary renin activity following angiotensin II infusion were all remarkably attenuated by intramedullary PRO20 infusion." (PMID 26554902, 2015). "Elevated insulin levels also stimulate the renin–angiotensin–aldosterone system (RAAS), contributing to increased glomerular pressure, endothelial injury, and glomerulosclerosis." (PMID 39940350, 2025). "Glomerulosclerosis and the decrease in effective (perceived) blood flow in CKD patients result in excess renin release, an increase in circulating Ang II levels, and AT1R upregulation." (PMID 36835994, 2023). "Accordingly, the db/db UNx-Renin mouse presents with hallmarks of late-stage DKD, including markedly increased urine albumin-to-creatinine ratio (ACR), advanced glomerulosclerosis and elevated serum creatinine levels." (PMID 34494644, 2021). "Activation of the renin-angiotensin-aldosterone system (RAAS) leads to renal hypoxia, vasoconstriction, intraglomerular hypertension, glomerulosclerosis and proteinuria." (PMID 23382907, 2013). "Vitamin D/vitamin D analog therapy has been shown to decrease glomerulosclerosis by suppressing the actions of TGF-β, albuminuria, podocyte hypertrophy, mesangial cell proliferation, and activation of the renin-angiotensin system." (PMID 22533967, 2012). "To summarize, measurements indicate that a single injection with ReninAAV exacerbates kidney injury, notably albuminuria and glomerulosclerosis, in UNx-renin mice compared with UNx mice, but does not affect body weight or blood glucose levels." (PMID 34494644, 2021). "In addition to classical renin/ACE/Ang II/AT1 and AT2 axis, recent studies have shown that multiple new members of RAS system play critical role in both glomerularsclerosis and tubularsclerosis, with synergic or antagonistic effect to classical RAS." (PMID 25954204, 2015). "Thus, after ischemic injury, loss of nephron mass with hyperfiltration of the residual nephron, activation of the renin-angiotensin system (RAS), systemic hypertension, and subsequent glomerulosclerosis, have been described to pave the way from AKI to chronic renal failure." (PMID 36497080, 2022).
resistant hypertension (46 papers, 2010 to 2026). "ARAs have also been associated with resistant hypertension owing to their suggested role in activating the renin‐angiotensin‐aldosterone system." (PMID 39648312, 2025). "The largest study to date from 3 African countries examined several variants of genes implicated in low renin-resistant hypertension in Africans with suppressed renin and increased aldosterone." (PMID 30832344, 2019). "A recent report using genetic sequencing of genes implicated in sodium and water retention in African Americans revealed variants associated with amino acid changes were implicated with low renin resistant hypertension." (PMID 30832344, 2019). "Resistant hypertension is a common clinical problem in South Africa and is frequently associated with low renin and aldosterone levels, especially in black Africans." (PMID 29144530, 2017). "The superior response to spironolactone, compared with the other drugs, particularly in patients at the lower end of the distribution of plasma renin, supports the hypothesis that the predominant cause of resistant hypertension is sodium retention." (PMID 26414968, 2015). "Although MRAs have been used primarily for blood pressure control in patients with PA and resistant hypertension, recent data indicate that the risk of cardio-renal complications is reduced only in patients with adequate MR blockade, as suggested by reversal of renin suppression." (PMID 33841329, 2021). "Emerging research has revealed a wide spectrum of renin-independent aldosteronism, ranging from subclinical disease with normal or mildly elevated BP to overt disease marked by resistant hypertension and cardiovascular complications." (PMID 40863169, 2025). "This study aimed to identify the cutoff values of aldosterone levels (A) and the aldosterone–renin ratio (ARR) for an accurate prediction of PA in patients with apparent resistant hypertension in a real-life scenario." (PMID 39452270, 2024). "A series of simulations identified concepts directly related to COVID-19 and resistant hypertension or connected via one of three renin–angiotensin–aldosterone system hub nodes (mineralocorticoid receptor, epithelial sodium channel, angiotensin I receptor)." (PMID 37759668, 2023). "Resistant hypertension (RH) is defined as the failure to achieve blood pressure control despite using triple combination therapy with a renin-angiotensin system inhibitor (RAS-i), a calcium antagonist, and a diuretic." (PMID 36983961, 2023). "Definition of normal ranges for plasma renin is difficult in patients receiving multiple antihypertensive drugs—in particular the A+C+D classes required for a diagnosis of resistant hypertension, all of which increase concentrations of plasma renin." (PMID 29655877, 2018). "Findings from two observational studies had suggested that plasma renin concentrations were often more suppressed than anticipated in patients with resistant hypertension, consistent with this being a sodium-retaining and volume-expanded state." (PMID 29655877, 2018). "It is probable that plasma renin in resistant hypertension is relatively suppressed by sodium retention, even though absolute values appear normal or high." (PMID 26414968, 2015). "We hypothesize that renovascular abnormalities contribute to resistant hypertension primarily through the activation of the renin–angiotensin–aldosterone system." (PMID 40004797, 2025). "Hyperactivity of this system, frequently observed in resistant hypertension, contributes to chronic blood pressure elevation by stimulating the renin-angiotensin-aldosterone system, promoting sodium and water retention, and inducing persistent vasoconstriction." (PMID 41333717, 2025).
resistant hypertension (continued). "Resistant hypertension (RH) defined as uncontrolled blood pressure despite the use of a combination of a renin-angiotensin system blocker, a calcium channel blocker, and a diuretic at maximally tolerated doses is associated with a substantially increased risk of cardiovascular and renal events." (PMID 37566184, 2023). "For example, new classes of drugs targeting the renin-angiotensin-aldosterone system or the sympathetic nervous system are currently in development and may prove effective in treating resistant hypertension." (PMID 37416924, 2023). "Moreover, the SNS innervates the kidneys, playing a major role in the pathophysiology of resistant hypertension via the renin–angiotensin–aldosterone system (RAAS) and sodium absorption." (PMID 34748053, 2022). "Shimosawa T. Salt, the renin-angiotensin-aldosterone system and resistant hypertension." (PMID 32267335, 2020). "In a prospective study of 88 consecutive patients referred to a university clinic for resistant hypertension, researchers reported that 18 (20%) had increased urinary aldosterone and suppressed plasma renin concentrations, despite salt intake in excess of 200 mmol/24 h." (PMID 29655877, 2018). "Furthermore, an increased aldosterone-renin ratio in patients with resistant hypertension is considered a predictor of exacerbated cardiovascular injury, in addition to increasing the risk of developing uncontrolled resistant hypertension." (PMID 27347925, 2016). "Mechanistic haemodynamic substudies, which could add to the predictive value of renin and help us to understand the pathophysiology of resistant hypertension, were included at most sites and will be reported separately." (PMID 26414968, 2015). "One hypothesis is that resistant hypertension is due to abnormal sodium retention, mediated by aldosterone breakthrough occurring despite blockade of the renin-angiotensin-aldosterone system with angiotensin converting enzyme inhibitors (ACEi) or angiotensin receptor blockers (ARB)." (PMID 27072827, 2016). "In the patients with resistant hypertension in PATHWAY-2, this point lies at the extreme right of the renin distribution, with all but 3% of patients predicted to respond better to diuretic than RAS blocker." (PMID 29655877, 2018). "Patients with resistant hypertension (RH), however, are characterized by a dysregulated renin-angiotensin-aldosterone system, even in the absence of PA." (PMID 37223051, 2023). "The concept of Prof. Laragh has recently been confirmed in a study conducted in patients with resistant hypertension (PATHWAY-2), in which the antihypertensive efficacy of drugs acting through the renin–angiotensin system depended on the baseline plasma renin activity." (PMID 35269797, 2022). "The results from our study also confirms that in non-stimulated conditions, patients with resistant hypertension have a down-regulated RAAS with a low renin activity and a low aldosterone, which is not stimulated by LBNP." (PMID 29876358, 2018). "In addition, several factors including oxidative stress, fibrosis, andactivation of the renin-angiotensin system (RAS) are involved in the pathogenesis ofrenal injury and lead to the impaired control of RSNA and resistant hypertension." (PMID 28076452, 2017).